PRF1 (perforin 1)
Diseases named in the same sentence as PRF1 in open-access papers (continued):
Sharing a sentence is not in itself a finding about the gene and the disease.
tumor (continued). "As for T cell related cytotoxins, essential in tumor killing, stacked FPKM of 8 genes (PRF1, GZMM, GZMK, GZMH, GZMB, GZMA, FASLG, and FAS) demonstrated that these genes were more highly expressed 1.7-fold (P = 0.037) in IFNγ positive tumors compared to IFNγ negative tumors." (PMID 32265897, 2020). "GZMA can lead to apoptosis without cascade activation, and PRF1 can help the granzyme enter and kill tumor cells." (PMID 33254149, 2020). "Increased CD3+ T-lymphocyte and CD8+ T-cell tumor infiltration in RANK−/− tumors compared with RANK+/+ was confirmed by IHC and the mRNA levels of the cytotoxicity markers, namely Ifnγ and perforin (Prf1) were higher in RANK−/− tumors." (PMID 33303745, 2020). "Specifically, we observed favorable tumor infiltrating lymphocyte expression in these 17 tumor samples from our deconvolution analysis (e.g., more CD8+ T cells, less M0 macrophages) and augmented CD8+ T cell activation expression (e.g., CD8A/B, PRF1, HLA-A)." (PMID 29928512, 2018). "PRF1 expression was decreased 1.5 fold in CD8+ T cells from tumor compared to PBMC although not significant (p = 0.526)." (PMID 29966014, 2018). "In T cell-mediated anti-tumor immunity, CD8+ cytotoxic T cells recognize MHC class I antigens on the tumor cell surface via T cell receptor to trigger the release of granzyme A (GZMA) and perforin (PRF1) to kill tumor cells." (PMID 28977839, 2017). "For Eckhard, the observation that Perforin-1 in CD8+ CTL and NK cells may be involved in killing tumor cells was also personally important." (PMID 27857713, 2016). "Additionally, to estimate immune cell prevalence we used the average expression of the lymphocyte-specific genes GZMB, PRF1, CXCL13, IRF1, IKZF1, and HLA-E in each tumor sample." (PMID 27959926, 2016). "Furthermore, both types of tumor-EVs induced a more tumor promoting macrophage phenotype in vitro, such as increased endocytosis and expression of TAM/M2 markers/cytokines and decreased cytolytic activity (Prf1)." (PMID 27550147, 2016). "Still in the untreated tumor, when compared to NBTXR3 + XRT + αPD1, NBTXR3 + PRT + αPD1 treatment resulted in a significant increase in the expression of activation markers such as Gzmb, Icos, Prf1 (Perforin 1), as well as chemokine receptor (Ccr7), and chemokine ligand (Ccl5) in cytotoxic T cells." (PMID 39354474, 2024). "Additionally, we speculated that tumor cells affected NK cells and promoted the generation of MPE in LUAD via the exosomal hsa-miR-3120-5p-PRF1 axis." (PMID 36684253, 2022). "Additionally, we hypothesized that tumor cells affected natural killer cells and promoted the generation of PE in LUAD via the exosomal hsa-miR-3120-5p-PRF1 axis." (PMID 36684253, 2022). "In addition, stratified analysis showed that PRF1 and IL2RA might be involved in the mechanism of tumor progress." (PMID 36097539, 2022). "These genes were defined as the tumor reactive signature (TRS), including co-inhibitory receptors (CTLA4, PDCD1, TIGIT and HAVCR2), reactive markers (CD38 and ENTPD1), effector molecules (NKG7 and PRF1), tumor necrosis factor TNFRSF9 and critical exhaustion-related regulator TOX." (PMID 34804045, 2021). "Further, to interrogate whether the immune cells in the tumor samples exhibited anti-tumor activity or merely originated from blood vessels in the tumor tissue, we calculated the correlation of TIL score with expression of two known cytolytic markers, granzyme A (GZMA) and perforin (PRF1)." (PMID 33980253, 2021). "Finally, 8 genes related to anti-tumor immunity were obtained, which were APOL3, CCL5, CD8A, CD8B, CXCL9, GZMA, GZMK and PRF1.We found that the m6A regulatory factors YTHDC1, YTHDC2, and WTAP were positively correlated with m6A, while IGF2BP3 was negatively correlated." (PMID 34737950, 2021).
tumor (continued). "The expression of T cell cytotoxicity (CD3G, CD3E, CD4, GZMA, PRF1 and TBX21), B cell MHC II and immune exhausted-related genes were abundant in metastatic sites; while MHC I inflammation related genes (HLA-B, HLA-C and IL-1A) were mostly higher in primary than recurrent tumor sites." (PMID 33476333, 2021). "In line with this possibility, the over-expressed genes in LumA-R2 samples included genes typical of CTLs (and also natural killer (NK) cells), which may lead to anti-tumor cytotoxic activities exerted by the granzyme (GZMA and GZMB) and perforin pathways (PRF1)." (PMID 27386846, 2016). "The decrease in the levels of PRF1, a key effector molecule for cytolysis mediated by T and NK cells, in presence of CD8A and CD56 expression in PDAC suggests that the cytotoxic activity or the number of CD8+ T and NK cells may be reduced in the tumor." (PMID 25415223, 2014). "Interestingly, ORMDL3 expression showed a negative correlation with CD8+ T cell activation markers such as PRF1, GZMA, and GZMB, as well as with ISGs such as CCL5 and CXCL10, validating our finding that ORMDL3 serves as a negative regulator of the IFN signaling pathway and anti-tumor immunity." (PMID 40126553, 2025). "The absence of PRF1 may activate immune checkpoint pathways, such as the PD-1/PD-L1 pathway, leading to inactivation of T cells, reduced proliferation, and increased apoptosis, thus impairing their ability to recognize and attack tumor cells." (PMID 39199299, 2024). "In contrast, MNK inhibitors did not affect the expression of PD-1, Prf1, or CD69 in CD8+ T cells isolated from the spleens of tumor-bearing mice treated with MNK inhibitors in vivo." (PMID 35380995, 2022). "In addition, compared to Nb-BiTE or control group, Nb-TriTE induced higher GzmB and PRF1 secretion levels after incubation with FAP+ tumor cells, but no significant changes in FAP− HepG2 tumor cells." (PMID 38031188, 2023). "Also, MNK inhibitors did not affect the expression of PD-1, Prf1, or CD69 in CD8+ T cells isolated from the spleens of non–tumor-bearing mice and treated with MNK inhibitors ex vivo." (PMID 35380995, 2022). "Interestingly, our study revealed no increase in tumor abundance of T cell subsets, in HPV-positive HNSCC patients, contrary to previous reports suggesting that favorable prognosis in HNSCC patients was mediated by CD8+ GZMA+ PRF1+ T cells." (PMID 37111458, 2023). "Surprisingly, we did not observe a difference in GzmB or Prf1 expression between CD8+ T-cells isolated from MC38 tumors between groups, suggesting that impaired T-cell mediated anti-tumor immune responses are unlikely to explain the increased tumor burden observed in LysMCre/+;Mycfl/fl hosts." (PMID 36552868, 2022). "However, it is also notable that a series of genes that are expressed in activated CD8+ T cells (Gzmb, Prf1, Il2, Ifng, Tnf, Fasl) or in activated CD4+ T cells (Tgfb1, Cd40lg, Il2, Ifng, Tnf, Fasl) were not upregulated in the relevant CD8+ and CD4+ clusters in tumours versus normal." (PMID 40473819, 2025).
cancer (99 papers, 2010 to 2026). A tumor composed of atypical neoplastic, often pleomorphic cells that invade other tissues. "The analysis of the Kaplan–Meier plots for the most significant cancer association (LGG) with PRF1 gene CNV mutations revealed that in OS, PFS and DSS, deletion mutations were associated with adverse survival outcomes when compared to wild type." (PMID 40002821, 2025). "The analysis of copy number variation (CNV) mutations in GZMA, GZMB, GZMK and PRF1 across the various cancer types revealed significant associations with survival outcomes, highlighting their potential prognostic value." (PMID 40002821, 2025). "To further explore the impact of the SNV and CNV mutations in GZMA, GZMB, GZMK and PRF1 in the different cancers, we assessed the survival differences between mutant and wild-type forms of the genes." (PMID 40002821, 2025). "A variety of cancers, including head and neck cancer, esophageal cancer, and gastric cancer, are associated with poor prognosis when PRF1 expression is reduced or lost." (PMID 39199299, 2024). "In some cancers, high expression of the PRF1 gene is associated with a better prognosis for patients, possibly because it helps enhance the body’s immune response to tumors." (PMID 39199299, 2024). "Cancer-associated fibroblasts (CAFs) also display a suppressive activity that partially relies on PRF1 downmodulation in NK cells." (PMID 32466293, 2020). "Accordingly, mutation in the perforin coding gene (PRF1) increases the susceptibility to develop cancers." (PMID 29966014, 2018). "We next performed Kaplan–Meier survival analysis on 37 TCGA-datasets deriving from 25 different cancer types in order to estimate the risk of individual and/or simultaneous high (or low) PRF1 and GZMA expression on patient overall survival." (PMID 29515971, 2018). "Notably, prior studies have reported that missense mutations in the perforin (PRF1) gene contribute to hereditary cancer predisposition." (PMID 41048344, 2025). "Furthermore, MESO exhibited significant associations between both DSS and OS and PRF1 CNVs, highlighting their relevance in predicting survival outcomes across different cancer types." (PMID 40002821, 2025). "Moreover, we found that ACAP1 expression was strongly positively correlated with cytotoxicity score (CYT) and the expression of GZMA and PRF1, which encode two key cytolytic effectors (granzyme A and perforin 1), in most cancer types." (PMID 36497434, 2022). "Finally, IDO1 and the cytotoxic molecules including GZMA and PRF1 showed a positively stronger association with GMFG in most cancer types." (PMID 33863293, 2021). "Such technologies may validate the more common statistical approaches, where for example, the frequency of a PRF1 mutation in cancer patients is compared to that in healthy controls." (PMID 24376445, 2013). "Following the SNV analysis, we examined the proportion of heterozygous and homozygous mutations (both deletions and amplifications) in GZMA, GZMB, GZMK and PRF1 in the different cancers." (PMID 40002821, 2025). "Methylation of PRF1 was inversely correlated with RNA expression across most cancers, while the majority of genes in THCA also displayed negative correlations." (PMID 41150760, 2025). "In summary, the CNV analysis of GZMA, GZMB, GZMK and PRF1 across multiple cancer types highlighted a remarkable prevalence of heterozygous amplifications and deletions compared to homozygous variations." (PMID 40002821, 2025). "To determine the prognostic implications of GZMA, GZMB, GZMK and PRF1 across the different cancer types, we explored their Kaplan–Meier plots." (PMID 40002821, 2025). "Our findings align with those of recent studies emphasizing the significance of immune-related genes, specifically GZMA, GZMB, GZMK and PRF1, in cancer pathogenesis and clinical outcomes." (PMID 40002821, 2025).
cancer (continued). "In conclusion, our study underscores the multifactorial impact of GZMA, GZMB, GZMK and PRF1 and their potential as biomarkers for personalized cancer immunotherapy." (PMID 40002821, 2025). "Our results demonstrate that Tex markers are consistently expressed at varying levels, while the effector genes (IFNG, GZMB, and PRF1) show lower expression levels across most cancer types." (PMID 40076932, 2025). "It is indicative that the expression levels of both CYT markers (GZMA and PRF1) can predict the favorable prognosis of cancer patients who receive ICI therapy." (PMID 38612436, 2024). "Further in-depth studies and reviews are needed on the contradictory findings of PRF1 in cancer progression." (PMID 39199299, 2024). "Understanding the mechanism of PRF1’s role in immune escape can help scientists better understand cancer development and provide an important reference for the development of new therapeutic approaches." (PMID 39199299, 2024). "CYT is closely related with patient prognosis and outcomes and the expressions of both GZMA and PRF1 genes synergistically, or alone can affect the OS of cancer patients." (PMID 38612436, 2024). "But further studies are needed to elucidate the exact role of PRF1 in different cancer types and to determine the potential for its use as a prognostic biomarker." (PMID 39199299, 2024). "Although PRF1 remains controversial in terms of its role in cancer prognosis, there are a number of theories." (PMID 39199299, 2024). "It is important to understand that PRF1’s mechanism of action has a significant impact on the prognosis of cancer when it comes to treatment." (PMID 39199299, 2024). "To improve the therapeutic efficacy and survival rate of cancer patients, we can better understand the biological functions of PRF1." (PMID 39199299, 2024). "To conclude, PRF1 has an important biological function and has clinical potential for the treatment of cancer, which indicates that it deserves more research and development in the future." (PMID 39199299, 2024). "Studies have shown that aberrant PRF1 expression has a significant role to play in cancer development and progression." (PMID 39199299, 2024). "In cancer therapy, PRF1 is thought to play a role in promoting apoptosis and inhibiting cancer cell growth and spread." (PMID 39199299, 2024). "Cytolytic activity score was defined as the geometric mean of GZMA and PRF1 expression, which is a new index of cancer immunity representing the CD8+ T cell activation level." (PMID 37427097, 2023). "Complement factor C9 functions in targeting and eliminating extracellular bacteria; Perforin-1 is tasked with dealing with intracellular viruses and cancer cells; and Perforin-2 can eradicate both intra- and extracellular bacteria." (PMID 38249350, 2023). "CD8+ cytotoxic T cells had elevated expression of the cytotoxic markers PD-1, Gzmb, Gzmk, Prf1, Nkg7, Eomes, Irf8, Klrd1, Fyn, Nfatc1, Tnfrsf9, and Zap70, supporting their killing function against cancer cells." (PMID 37762216, 2023). "The increased cytotoxic gene expression (upregulated Prf1 and GzmB) in T cells found in chemo-sensitive tumors further substantiates the increased anti-cancer activity of IL-17A+ DOX sensitive tumors." (PMID 35924165, 2022). "At present, the relationship of RIPK2 with GZMB, NKG7 and PRF1 in cancer is still unclear, and this still needs to be explored in the occurrence, development, treatment and prognosis of cancer." (PMID 35473583, 2022). "CD8 + T cells can kill cancer cells by releasing PRF1, GNLY, or GZM and break tolerance as a preexisting immune response, enhancing immunotherapy via the PD-1/PD-L1 immune inhibitory axis." (PMID 34790235, 2021). "Secretion of the pore-forming molecule Perforin-1 and proapoptotic protease Granzyme B, which can lead to granule exocytosis of cancer cells, was induced by the administration of rSmeg-hMIF-hIL-7." (PMID 34389619, 2021).
cancer (continued). "Specifically, the mRNA expression levels of both granzyme A (GZMA) and perforin (PRF1) have been reported to be novel indicators of CYT cancer immunity." (PMID 34193146, 2021). "The antitumoral immune cytolytic activity (CYT), calculated from the mRNA expression of granzyme A (GZMA) and perforin 1 (PRF1), is a relatively new indicator of cancer immunity." (PMID 34316699, 2021). "In line with their synchronized roles, the expression of GZMA and PRF1 was strongly coordinated across the different cancer samples (Spearman rank correlation, rho = 0.87)." (PMID 29515971, 2018). "Protein expression profiles of granzyme A (GZMA) and perforin 1 (PRF1) across 19 different cancer types, using antibody-based protein profiling data from immunohistochemistry (the Human Protein Atlas)." (PMID 29515971, 2018). "We found that higher local immune activity (as measured by the mRNA levels of Granzyme A and Perforin-1) predicted smaller expression noise in cancers." (PMID 27713130, 2016). "Perforin-1 is therefore a key effector molecule for T-cell- and NK cell-mediated cytolysis of virus-infected and cancer cells." (PMID 27857713, 2016). "As a physician, he had a particular interest harnessing the power of the immune system to defeat cancer and Perforin-1 in NK cells and CD8+ CTL seemed to offer a path forward." (PMID 27857713, 2016). "Together with PRF1, these genes are excellent candidates, which we are investigating and currently analyzing in familial cancer aggregations including hematological malignancies." (PMID 21936944, 2011). "However, the challenges are not limited to the cancer cells’ membrane; they also arise from the insufficient activation of cytotoxic lymphocytes, leading to low concentrations of PRF1 released into the IS." (PMID 40691738, 2025). "In cytotoxic T cells/NK cells, we found that SUDV-induced IL-6 was predicted to induce SOCS3 expression and the downstream suppression of STAT5, granzyme B (GZMB) and PRF1 expression, leading to suppressed apoptosis of APCs and cancer cells, as well as pore formation." (PMID 41181097, 2025). "In regard to PRF1, while we believe our data look promising and in line with other research implicating PRF1′s role in poor prognosis in many cancer types, including UCEC, further research is warranted to determine how this protein impacts each cancer individually and the different functions it has." (PMID 40002821, 2025). "This investigation highlighted the diverse associations between DNA methylation of GZMA, GZMB, GZMK, and PRF1 and survival outcomes, displaying the potential prognostic implications of epigenetic modifications in immune-related genes across different cancer types." (PMID 40002821, 2025). "Some studies may support a positive role of PRF1 in cancer progression, while others may draw opposite conclusions." (PMID 39199299, 2024). "Furthermore, recent studies have explored therapeutic strategies based on PRF1, such as enhancing the ability of immune cells to kill cancer cells by boosting PRF1 activity." (PMID 39199299, 2024). "In summary, PRF1’s impact on cancer encompasses multiple aspects, such as biological function, treatment, and prognosis, and its mechanism of action is critical for improving cancer treatment and monitoring." (PMID 39199299, 2024). "Overall, PRF1’s role in cancer prognosis is complex and depends on multiple factors." (PMID 39199299, 2024). "Recent studies have focused on PRF1’s role in cancer development, progression, and prognosis." (PMID 39199299, 2024). "Therefore, an in-depth study of the function and mechanism of PRF1 will provide new ideas and strategies for cancer prevention, diagnosis, and treatment." (PMID 39199299, 2024). "An in-depth study of PRF1’s mechanism of action may provide an important reference for the treatment and prognosis of cancer, as well as provide increased hope for patient survival." (PMID 39199299, 2024).